BRAF (B-Raf proto-oncogene, serine/threonine kinase)
Diseases named in the same sentence as BRAF in open-access papers (continued):
Sharing a sentence is not in itself a finding about the gene and the disease.
melanoma (continued). "This variant is of special therapeutic interest, because vemurafenib, an inhibitor specifically targeting the activated step of the MAPK pathway induced by the mutated BRAF protein, is available, and treating human melanoma patients with this drug results in a transient remission of the disease." (PMID 35202309, 2022). "The prospectively collected data from the Canadian Melanoma Research Network (CMRN) includes patients with BRAF-mutated melanoma who were initiated on either immunotherapy or targeted therapy for first-line treatment, followed by the other for second-line treatment." (PMID 35323326, 2022). "Activating somatic mutations in the BRAF gene are detected in 6–8% of cases of solid tumors, including melanoma (in 44% of tumors), thyroid cancer (1.7–90.0%, depending on the tumor histological type), colorectal adenocarcinoma (10%), and lung adenocarcinoma (1.5–8.0%)." (PMID 37065428, 2022). "In addition, when applying MutSig2CV to identify significantly mutated genes, both NRAS and BRAF, known melanoma drivers, were found to be significantly mutated." (PMID 35654823, 2022). "The oncogenic mutation V600E in BRAF protein accounts for 50%–60% of the somatic mutations in melanoma leading to constitutive activation of the protein kinase BRAF and downstream induction of the MAP kinase/ERK-signaling pathway with correlated melanomagenesis." (PMID 35174094, 2022). "In addition to MECOM and BMP5 in BRAF-mutated melanoma, GNAQ or CNA11 mutations in uveal melanoma are also associated with TGF-β signaling." (PMID 35461253, 2022). "Moreover, patients with metastatic, recurrent, or inoperable melanoma harboring a BRAF mutation (V600E or V600K) are also candidates for targeted therapy, especially when a rapid response is clinically needed." (PMID 36589179, 2022). "Instead, number of metastatic sites > 2 (HR 2.195, 95%CI 1.302–3.699, p = 0.003), baseline brain metastasis (HR 1.833, 95%CI 1.073–3.130, p = 0.027), and baseline ECOG ≥ 2 (HR 3.957, 95%CI 2.226–7.034, p < 0.001) were significantly associated with worse OS in BRAF-mutant melanoma patients." (PMID 35323326, 2022). "Additional molecular classifiers included three brain metastases derived from HER2+ breast adenocarcinomas, one from a melanoma with the activating mutation BRAF V600E (Fig EV2R), and one from a gastro‐esophageal cancer without known oncogenic drivers sensitive to HSP90 inhibition (Fig EV2S)." (PMID 35174975, 2022). "Selective BRAF inhibition improves the outcomes of patients with mutated BRAF melanoma." (PMID 36014370, 2022). "Among the two melanoma cell lines used in this study, A375 is the most highly malignant because it displays low time of duplication, shows the activation of multiple oncogenic pathways, and carries a high pathogenic mutation in the BRAF gene." (PMID 35163058, 2022). "Moreover, when melanoma patients become resistant to BRAF/MEK inhibitors, increased copy numbers of MET mutations is detected in the ctDNA." (PMID 35974375, 2022). "A total of 176 participants with metastatic or BRAF-mutated unresectable melanoma were enrolled." (PMID 35742834, 2022). "Circulating tumor cells in melanoma patients had substantial upregulated pathways involved in lipogenesis and iron homeostatic pathways, correlated to drug-resistant circulating tumor cells harboring BRAF mutations." (PMID 35884561, 2022). "The BRAF V600 mutation is observed in approximately 50% of malignant melanomas." (PMID 35163049, 2022). "Previous studies have shown that DNA in EVs not only covers the entire genome of parental cells, but also allows identical mutations from the cells they are derived from to be detected, including clinically relevant mutations such as KRAS mutations in pancreatic cancer or BRAF in melanoma." (PMID 35805031, 2022). "•The combination of BRAF inhibitor/MEK inhibitor with immunotherapy may be a therapeutic option to reduce immune-mediated resistance in BRAF-mutated melanoma." (PMID 35492830, 2022).
melanoma (continued). "Interestingly, the antitumor effect of USP14 targeting is applicable to BRAFV600E-, NRAS-, and NF1-mutated melanoma cells and to BRAF/MEK inhibitor-resistant cells." (PMID 35884430, 2022). "Importantly, endogenous BRAF/MITF complexes were also evidenced in BRAF-mutated human melanoma cells, thus emphasizing the conservation of RAF/MITF interaction in human." (PMID 35091687, 2022). "Because BRAF-mutant melanomas are aggressive, it is critical to detect whether patients with melanoma have tumors with the BRAF mutation as soon as possible to choose the best treatment." (PMID 36589179, 2022). "ARID2 mutations are frequent in melanoma, independent from BRAF/RAS mutations status." (PMID 35334544, 2022). "Accordingly, the detection of PI3K–Akt mutations in melanomas may occur in BRAF (V600E/K)-mutated tumours conferring resistance to therapies." (PMID 35335966, 2022). "It has been used in vivo and in vitro in a model of BRAF mutated melanoma and reduces tumor growth." (PMID 35406721, 2022). "We show here that the anti‐fibrotic drug nintedanib (BIBF1120, Ofev®) improves the response of the BRAFi/MEKi‐targeted therapy in a preclinical model of melanoma and in BRAF‐mutated cell lines by preventing MAPKi‐induced lineage dedifferentiation, ECM reprogramming, and mesenchymal traits." (PMID 35156321, 2022). "The MC1R germline variation increases the risk of BRAF-mutant melanoma." (PMID 36551302, 2022). "Almost one-third of all evaluated melanomas were positive for a BRAF mutation." (PMID 35406577, 2022). "Compared to melanocytes, we found that several BRAF-mutated melanoma cell lines display high levels of RPB1 Ser2 and Ser5 phosphorylation, which could be indicative a higher CDK12 activity." (PMID 36309522, 2022). "Logistic regression analysis was performed to determine if the mutational status of the BRAF gene could be a predictive factor for the development of distant metastasis and melanoma mortality, considering all primary melanoma samples." (PMID 35326682, 2022). "However, recent findings showed that, in melanoma samples, mutated BRAF positively regulates activation of ERK5 that was highly correlated with melanoma proliferation by in vitro and in vivo studies." (PMID 35053510, 2022). "In addition to developmental contexts, ERK signalling has also been reported to induce FOS gene expression downstream of oncogenic lesions, such as activating mutations in the BRAF gene, which frequently occur in in human melanomas." (PMID 36077499, 2022). "Moreover, miR-125b and miR-205 expression were also independent prognostic factors for melanoma-specific survival (MSS) in the BRAF mutated group." (PMID 35326682, 2022). "The frequency of activating BRAF mutations in malignant melanoma cases reaches 50%–60%." (PMID 36091815, 2022). "The high prevalence of BRAF mutations in cancer has spurred interest in the development of specific BRAF inhibitors: Vemurafenib was the first BRAF inhibitor approved for the treatment of metastasized melanoma harboring BRAF V600E mutations in 2011." (PMID 36275468, 2022). "Data from an international retrospective analysis of the response to BRAF/MEK inhibition in 96 advanced melanoma patients with rare BRAF V600 (n = 58) and non-V600 mutations (n = 38) revealed an overall response in 45% of V600 mutated patients but only 18% of non-V600 patients [13••]." (PMID 35380338, 2022). "Considering the key role of mutated V600E BRAF in promoting melanoma growth and aggressiveness, we wondered whether ITF2357 could target this protein or modify its expression levels." (PMID 36009541, 2022). "The idea that NRAS-driven melanoma might be more sensitive to immunotherapy may relate to the slightly higher average number of mutations in these tumors compared to BRAF-driven tumors." (PMID 35234863, 2022). "Hence, to further support our findings, experimental validation using additional BRAF-mutated melanoma cell lines or patient samples is recommended." (PMID 35214043, 2022).
melanoma (continued). "In melanoma, a liquid biopsy might represent a valuable tool for the detection of typical mutations in BRAF and NRAS genes, microsatellite alterations, and epigenetic modifications such as DNA methylation." (PMID 36295075, 2022). "Activating MAPK pathway through BRAF mutation may be a potential molecular target to overcome melanoma cells escaping immune surveillance." (PMID 36124033, 2022). "BRAF V600E mutation drives uncontrolled cell growth in most melanomas." (PMID 36358868, 2022). "In addition, we used UACC62 melanoma cells that carry a BRAF mutation and therefore exhibit constitutively active MAPK signaling." (PMID 36080182, 2022). "Somatic BRAF mutations have been found in nearly 60% of all melanoma, of which almost 90% harbor the V600E mutation, which results in the constitutive activation of MEK and ERK signaling, leading to increased cellular proliferation and survival and cancer progression." (PMID 36613518, 2022). "In light of guidelines for BRAF V600 mutated melanoma, dual-targeted therapy is also recommended." (PMID 35912223, 2022). "To demonstrate that the visual barcodes and a signalome system can be readily applied to other cell lines we generated two more signalome cell lines using the PC9 EGFR-mutated non-small-cell lung cancer cell line and the SK-MEL-5 BRAF-mutated melanoma cell line." (PMID 35585055, 2022). "In addition, targeted therapy for melanoma is primarily an appropriate treatment based on BRAF and NRAS mutational status." (PMID 36601121, 2022). "Although we did not observe any toxicity in the mouse model, long-term application in patients needs to be carefully surveilled and clinical trials are needed to investigate this interesting combination to improve the results of targeted therapy of BRAF mutated malignant melanoma." (PMID 35406796, 2022). "Moreover, this expression appeared constitutive and independent of the tumor mutational status, as it was observed in all cell lines tested that presented the most common melanoma-associated mutations, namely BRAF/V600E, NRAS/Q61K and NF1." (PMID 35428910, 2022). "Furthermore, we revealed that MrgprF low expression positively correlates with RAS and BRAF mutations in the CCLE melanoma dataset." (PMID 35504869, 2022). "Of note, although immunotherapy is often utilized as a salvage option after disease progression to MAPKi in BRAF-mutated melanoma patients, important studies suggest that acquired resistance to MAPK-targeted therapy 6 is a negative factor for subsequent response to immunotherapy 7-10." (PMID 36438490, 2022). "Targeted therapy options are scarcer for patients with non-BRAF-mutated melanoma." (PMID 35234863, 2022). "BRAF inhibitors (BRAFi), such as dabrafenib and vemurafenib, have shown excellent response rates and, in addition, MEK1/2 inhibitors, such as trametinib, binimetinib, and cobimetinib, have been approved in melanoma and non-small cell lung cancer with mutated BRAF." (PMID 36612117, 2022). "Moreover, it is discovered that melanoma cells with BRAF mutation are highly dependent on leucine, the deprivation of which results in defective autophagy in tumor cells and thus reveals a targetable liability." (PMID 36003368, 2022). "Analysis of BRAF mutation status is already standard procedure in diagnosing melanoma." (PMID 36232957, 2022). "BRAF-mutated melanomas are characterized by a higher aggressiveness and progression." (PMID 35684471, 2022). "ATP2B4, as a gene participating the transportation of Ca2+, has been confirmed that its overexpression could inhibit the progress and migration of melanoma cells with BRAF mutation." (PMID 35097120, 2022). "In fact, they found that acetoacetate as a ketone metabolite could induce BRAF V600E mutant-dependent mitogen-activated protein kinase 1 (MEK1) activation in melanoma cells, and KD might play a pathogenic effect in this cancer." (PMID 36079756, 2022).
melanoma (continued). "When BRAF-mutated melanomas rely on additional signaling molecules such as RAS for tumor growth, greater benefit may be expected from MEK inhibition than BRAF inhibition." (PMID 35380338, 2022). "Activating mutations of BRAF alone are inadequate to drive melanoma formation." (PMID 35768444, 2022). "The development of BRAF inhibitors, together with the incorporation of MEK inhibitors (the main resistance mechanism), has made targeted therapy the standard treatment for patients with BRAF-mutated melanoma both in metastatic disease and in the adjuvant scenario." (PMID 35203494, 2022). "Consequently, numerous studies have identified different BRAF inhibitors that target this tumor-promoting mutation, many of which have been approved for the treatment of melanoma patients." (PMID 36551563, 2022). "For example, fibroblast-derived ECM abrogated anti-proliferative responses to BRAF/MEK inhibition in BRAFV600-mutated advanced melanoma and pharmacological targeting of key molecules could overcome drug resistance." (PMID 35875109, 2022). "We hypothesized that the concomitant targeting of both MAPK and PI3K–Akt pathways in a PIK3CA-mutated melanoma model resistant to BRAF and MEK inhibitors would result in a better therapeutic efficacy that reverts drug resistance mechanisms." (PMID 35335966, 2022). "Approximately, 50% of melanoma cells have a mutated copy of BRAF oncogene." (PMID 35163615, 2022). "The most important mutation in melanomas—BRAF—is detected in 66% of malignant melanomas." (PMID 36613640, 2022). "Moreover, MOK belongs to the same MAPK superfamily, as MEK1 and MEK2 proteins, which have crucial roles in tumorigenesis and whose inhibition is currently an attractive strategy in melanomas with BRAF mutation." (PMID 35993275, 2022). "BRAF mutations represent a frequent event in oncogenesis, mainly in melanoma." (PMID 36614156, 2022). "Benign nevi often harbor BRAF mutations but only rarely progress to melanoma." (PMID 35234863, 2022). "As previously suggested, this may indicate that the BRAF V600E mutated melanomas on acral skin are likely different and more akin to cutaneous melanomas on skin with low cumulative sun-induced damage." (PMID 35706047, 2022). "BRAF mutational status is usually an important factor for melanoma." (PMID 36131912, 2022). "It had the effect of synergistic anti-BRAF (v-raf murine sarcoma viral oncogene homolog B1) mutation melanoma cell proliferation with RAF kinase inhibitor, and synergistic anti-ALK (anaplastic lymphoma kinase) mutation neuroblastoma with ALK inhibitor and prolonged survival." (PMID 35831864, 2022). "Later analyses of genetic data from multiple clinical trials of BRAF inhibitors in melanoma found putative resistance-causing mutations in 58–74% of progressive tumors and confirmed the reactivation of the RAS/MAPK pathway itself as the major cause of resistance to targeted therapy." (PMID 35234863, 2022). "However, this correlation is weak as NRAS or BRAF mutations are found in approximately 80% of melanomas and cannot be used as reliable clinical predictor of hepatic metastasis." (PMID 35109875, 2022). "In BRAF-mutated melanoma, the response rate to combined BRAF and MEK inhibitors is around 70%." (PMID 35327519, 2022). "Vemurafenib is often used in BRAF-mutated melanoma and is gradually being explored in BC." (PMID 36524001, 2022). "An important study was conducted to evaluate whether fisetin caused the anti-invasive as well as anti-metastatic potential of sorafenib in BRAF-mutated melanoma." (PMID 36558146, 2022). "The present study provides evidence that a dose of 150 mg b.d dabrafenib as currently administered to patients with BRAF-mutated malignant melanoma might be too high, and in the long run, may therefore lead to counter-intuitive ramifications." (PMID 35214043, 2022). "The most frequent type of mutations in melanoma are mutations in the BRAF oncogene (>60% of cases)." (PMID 35883549, 2022).
melanoma (continued). "Importantly, endogenous BRAF/MITF complexes were also detected in BRAF-mutated human melanoma cells." (PMID 35091687, 2022). "Eight patients (27%) had a high LDH level, and 24% had a BRAF-mutated melanoma." (PMID 35804963, 2022). "(B) The cancer cells have BRAF gene mutation in about half of all melanomas." (PMID 36407184, 2022). "Targeted treatment with BRAF and MEK inhibition has demonstrated clinical efficacy in melanomas harboring the BRAF-V600E/K mutation, and the combination of dabrafenib and trametinib, vemurafenib, and cobimetinib represent effective therapeutic options for these patients." (PMID 36585710, 2022). "Moreover, only a limited number of reports are available to describe long-term treatment efficacy for patients with BRAF mutated melanoma, as—in general—trials offering treatment beyond the frontline setting are rarely designed." (PMID 35456332, 2022). "BRAF mutation is the most common gene mutation in patients with melanoma." (PMID 36387162, 2022). "Because NRAS Q61K, KRAS G13D, and MEK1 Q56P mutations are associated with BRAF inhibitor resistance in BRAF V600E melanoma, we first tested each A375 model cell line for resistance to the FDA-approved BRAF inhibitor compounds dabrafenib and vemurafenib in 2D tissue culture." (PMID 36358868, 2022). "We hypothesize that BRAF-mutated mucosal melanomas, which are often encountered at a late disease stage, could actually represent metastasis of fully regressed or never-detected cutaneous melanomas." (PMID 34142226, 2022). "Also, several studies have shown that BRAF amplification signaling in BRAF V600E-mutated melanomas can cause spontaneous dimerization of the ensuing molecule, and this dimerization is able to reactivate the MAPK/ERK pathway." (PMID 36143375, 2022). "Additionally, CSF is enriched in ctDNA compared to plasma and tumor BRAF mutation has been detected and was informative of disease course in melanoma patients with leptomeningeal involvement." (PMID 36704194, 2022). "G18.EE and its fractions revealed a pro-oxidant activity in BRAF-mutated melanoma cells." (PMID 35684471, 2022). "The outcomes that changes in diet and use of antibiotics, probiotics or FMT may lead to in carcinogenesis and response to therapy may help us deepen our comprehension of how to approach patients with BRAF-mutated melanoma." (PMID 36233289, 2022). "All patients except for 3 (patients 13, 15, and 18) had BRAF V600E-mutated melanoma." (PMID 35213727, 2022). "Due to their rare nature and exclusion from larger drug approval studies, fewer data exist on the efficacy of BRAF inhibition and/or MEK inhibition in less frequent BRAF mutants, which account for approximately 3.4–14% of BRAF-mutated melanomas [2, 5•, 8, 11–12]." (PMID 35380338, 2022). "The results obtained were confirmed in FO1 cells, another BRAF-mutated melanoma cell line." (PMID 35163570, 2022). "Hence, on par with immune checkpoint inhibitors, these are the recommended first-line therapies for advanced melanomas harboring a BRAF V600E or V600K mutation." (PMID 35380338, 2022). "V600K Melanoma patients account for 10% of all BRAF mutated melanoma." (PMID 35160279, 2022). "Melanoma driver genes, including BRAF, have been implicated in the regulation of cellular energy metabolism, which has been shown to undergo reprogramming, being characterized by plasticity that facilitates melanoma progression and drug resistance." (PMID 35912092, 2022). "BRAF mutated melanoma arose more frequently in the Caucasian population compared to other ethnicities and it may be also linked to the effect of CSD on the fair skin phototype." (PMID 35160279, 2022). "BRAF mutation is seen in 59% of patients with malignant melanoma." (PMID 35308763, 2022).